RPS5 (ribosomal protein S5)
Description:
Component of the small ribosomal subunit. The ribosome is a large ribonucleoprotein complex responsible for the synthesis of proteins in the cell. Part of the small subunit (SSU) processome, first precursor of the small eukaryotic ribosomal subunit. During the assembly of the SSU processome in the nucleolus, many ribosome biogenesis factors, an RNA chaperone and ribosomal proteins associate with the nascent pre-rRNA and work in concert to generate RNA folding, modifications, rearrangements and cleavage as well as targeted degradation of pre-ribosomal RNA by the RNA exosome.
Synonyms: S5; uS7
Tractability: Small molecule: an approved drug acts on it; a structure with a bound ligand is known; a high-quality ligand is known. PROTAC: UniProt records ubiquitination sites on it; ubiquitination databases record sites on it; its protein half-life has been measured; a small molecule that binds it is known. Other modalities: a drug acting on it is in phase 2 or 3 trials.
Target class: Other cytosolic protein
Gene: Protein-coding gene on chromosome 19 (58,380,570 to 58,394,807, forward strand). Ensembl gene ENSG00000083845.
Subcellular location: Cytoplasm; Nucleus, nucleolus
Subcellular location (Human Protein Atlas): Cytosol; Endoplasmic reticulum
Pathways (Reactome):
Metabolism of proteins: Eukaryotic Translation Termination; Formation of a pool of free 40S subunits; Formation of the ternary complex, and subsequently, the 43S complex; GTP hydrolysis and joining of the 60S ribosomal subunit; L13a-mediated translational silencing of Ceruloplasmin expression; PELO:HBS1L and ABCE1 dissociate a ribosome on a non-stop mRNA; Peptide chain elongation; Ribosomal scanning and start codon recognition; SRP-dependent cotranslational protein targeting to membrane; Translation initiation complex formation; ZNF598 and the Ribosome-associated Quality Trigger (RQT) complex dissociate a ribosome stalled on a no-go mRNA
Disease: SARS-CoV-1 modulates host translation machinery; SARS-CoV-2 modulates host translation machinery; Viral mRNA Translation
Metabolism of RNA: Major pathway of rRNA processing in the nucleolus and cytosol; Nonsense Mediated Decay (NMD) enhanced by the Exon Junction Complex (EJC); Nonsense Mediated Decay (NMD) independent of the Exon Junction Complex (EJC)
Cellular responses to stimuli: Response of EIF2AK4 (GCN2) to amino acid deficiency
Developmental Biology: Regulation of expression of SLITs and ROBOs
Metabolism: Selenocysteine synthesis
Gene Ontology:
Molecular function: mRNA binding; protein binding; RNA binding; structural constituent of ribosome; rRNA binding
Biological process: regulation of translational fidelity; ribosomal small subunit biogenesis; translation; cytoplasmic translation; translational initiation
Cellular component: cytoplasm; cytosol; cytosolic ribosome; cytosolic small ribosomal subunit; endoplasmic reticulum; extracellular exosome; focal adhesion; membrane; ribonucleoprotein complex; small-subunit processome; nucleoplasm; ribosome; nucleolus; small ribosomal subunit; synapse
Genetic constraint (gnomAD): Loss-of-function variants: 2 observed, 20.09 expected, observed/expected ratio (o/e) 0.0995, 90% interval 0.04 to 0.31. The upper end of that interval is the gene's LOEUF score, 0.31, which puts it in group 1 of 6, group 1 being the genes least tolerant of losing a copy. Missense variants: 122 observed, 292.37 expected, observed/expected ratio (o/e) 0.42, 90% interval 0.36 to 0.49. Synonymous variants: 111 observed, 109.23 expected, observed/expected ratio (o/e) 1.02, 90% interval 0.87 to 1.19.
Homologues: Orthologues: chimpanzee RPS5 (100% identical), guinea pig RPS5 (100% identical), macaque RPS5 (100% identical), pig RPS5 (100% identical), rabbit RPS5 (100% identical), rat Rps5 (99% identical), mouse Rps5 (99% identical), zebrafish rps5 (96% identical), tropical clawed frog rps5 (94% identical), Drosophila melanogaster RpS5a (89% identical), dog RPS5 (87% identical), Drosophila melanogaster RpS5b (86% identical), and 1 more. Paralogues in human: MRPS7 (20% identical).
Diseases named in the same sentence as RPS5 in open-access papers:
RPS5 is named in the same sentence as 32 diseases in open-access papers, as found by Europe PMC text mining. Sharing a sentence is not in itself a finding about the gene and the disease. The quoted sentences say what the papers report.
liver fibrosis (5 papers, 2020 to 2025). "Ribosomal protein S5 (RPS5) is closely associated with liver fibrosis in Sprague-Dawley rats." (PMID 34798813, 2021). "In addition, RPS5 is clearly associated with the progression of hepatic fibrosis." (PMID 36834797, 2023). "Remarkably, CEP-1347, a therapeutic agent for chronic liver disease and liver fibrosis, targets RPS5 to inhibit the expression of p70S6K and the activation of hepatic stellate cells, effectively blocking the progression of liver fibrosis." (PMID 40521004, 2025). "RPS5 was also found to participate in extra-ribosomal activities such as cell differentiation, intracellular trafficking, and hepatic fibrosis." (PMID 32117819, 2020).
breast carcinoma (3 papers, 2017 to 2023). "We identify RPSA, RPS5, RPS20, RPL5, RPL11 and RPL23A as six interesting cancer driver candidates and show a tumor suppressor role for RPL5 in the context of breast cancer." (PMID 28147343, 2017).
Diamond-Blackfan anaemia (2 papers, 2007 to 2022). "Mutations in RPS19, RPS28, RPS10 and RPS5 result in the ribosomopathy Diamond-Blackfan anaemia." (PMID 34283226, 2022).
viral infection (2 papers, 2016 to 2023). "The difference in RPS5 binding ribosomal protein before and after viral infection elucidates the molecular mechanism of RPS5 promoting viral protein translation at the cellular level." (PMID 36834797, 2023).
colorectal cancer (1 paper, 2022). A primary or metastatic malignant neoplasm that affects the colon or rectum.
liver disease (1 paper, 2023). "Determining the functions corresponding to the structural domains or sites of RPS5 and modeling the interaction l of drug molecules with RPS5 will greatly contribute to the development of new drugs for the treatment of liver diseases and cancers." (PMID 36834797, 2023). "The role of RPS5 in translation initiation and its potential use as targets for liver disease and cancer are discussed." (PMID 36834797, 2023).
lung carcinoma (1 paper, 2022). "To determine whether RPS5 is involved in sensitivity to MEK inhibition, we knocked down RPS5 using siRNA in HCT116 cells and A549 human lung cancer cells harboring RAS mutation." (PMID 36713317, 2022).
osteoporosis (1 paper, 2020). A condition of reduced bone mass, with decreased cortical thickness and a decrease in the number and size of the trabeculae of cancellous bone (but normal chemical composition), resulting in increased fracture incidence. "Moreover, some studies have identified that a novel factor named ribosomal protein S5 (RPS5) could regulate NF‐κB, MAPK and AKT signalling pathways, which seems to be a promising target for osteoporosis treatment." (PMID 32681612, 2020).
osteosarcoma (1 paper, 2020). A usually aggressive malignant bone-forming mesenchymal neoplasm, predominantly affecting adolescents and young adults. "Next, we compared thetranscriptional stability of several normalizers that were formerly recommendedfor use in canine osteosarcoma without transcriptome-wide expression profiling forthis context such as OAZ1 or B2M,HNRNPH, RPS5 and RPS19." (PMID 32296879, 2020).
psoriatic arthritis (1 paper, 2022). Joint inflammation associated with psoriasis. "RPS5 is highly expressed in psoriatic arthritis and is expected to become a biomarker." (PMID 35841000, 2022).
infection (16 papers, 2009 to 2025). The state of being infected such as from the introduction of a foreign agent such as serum, vaccine, antigenic substance or organism. "The stability ranking at different developmental stages associated with infection of PWN was as the following: TER > RPL7 > RPS5 > Zdhhc15 > EF1-γ > RPL18 > Tmub1 > SNX6 > ATPase > TFAM > α-TUB > EIF > TPI > COX7." (PMID 35547586, 2022). "Among all samples, RPL7 and RPS5 were the most stable reference genes, similar with the results found in the sample sets of different developmental stages associated with infection of PWN and all PWN treatment conditions." (PMID 35547586, 2022). "TER, RPL7, and RPS5 were the optimal reference genes at different developmental stages associated with infection of PWN." (PMID 35547586, 2022). "In contrast, the biological processes downregulated with infection include ribosomal biogenesis (Rpl3, Rpl37, Rps5, Rpl11, Rplp1, Rpl28, Rpl19, Rps28, Rps14)." (PMID 35789215, 2022). "For different developmental stages associated with infection of PWN and pupae treated with PWN, two conditions had similar results that RPS5, RPL18, and RPL7 were identified as the most stable genes, but α-TUB, COX7, EIF, and SNX6 were poor stable genes." (PMID 35547586, 2022). "In this case, the use of highly stable reference genes (tbp-af and rps5) evidenced down-regulation of imd expression in infected bees whereas the use of one of the least stable genes (ef1-α) pointed to up-regulation of imd expression after infection." (PMID 31776359, 2019). "RPS5 declined during ARF may good for pathogen infection which will help the development of adventitious roots of chrysanthemum." (PMID 24369042, 2013). "Moreover, RPS5, AHCYL1 and AP2A2, host factors with presumed proviral roles in IAV infection, were enriched upon infection in our system." (PMID 40623098, 2025). "(2014) determined that the presence of the R-genes RPM1 and RPS5 in the absence of pathogen infection reduced seed production by ~10%." (PMID 37965025, 2023).
cancer (11 papers, 2017 to 2024). A tumor composed of atypical neoplastic, often pleomorphic cells that invade other tissues. "Experiments further confirmed the impact of RPS5 on pivotal cellular processes implicated in cancer progression, including cell proliferation and metastasis." (PMID 38255847, 2024). "In vivo and in vitro experiments further confirmed the impact of RPS5 on pivotal cellular processes implicated in cancer progression, including cell proliferation and metastasis, suggesting its involvement in the unrestrained growth characteristic of malignancy." (PMID 38255847, 2024). "Consistently, trametinib induced cell death in RPS5-depleted cancer cells via upregulation of the apoptotic proteins BIM and PUMA." (PMID 36713317, 2022). "According to these criteria, five genes (RPL5, RPL11, RPS5 (uS7), RPS20 (uS10), RPSA (uS2)) were significantly mutated in four different cancer types." (PMID 28147343, 2017). "From the gene-interaction network analysis, we found that the genes with survival-associated AS events including HNRNPA1, RPS5, DDX55, and OFD1 were hub nodes of the network which might play vital roles in cancer progress." (PMID 32595697, 2020). "In addition to its involvement in fibrotic liver diseases, RPS5 also correlates with some cancers." (PMID 36834797, 2023). "A recent study identified six ribosomal protein genes as potential cancer drivers in five different cancer types: uL18/RPL5, uL5/RPL11, uL23/RPL23A, uS7/RPS5, uS10/RPS20, and uS2/RPSA82." (PMID 29674660, 2018). "We screened mutation and copy number data of respectively 4926 and 7322 samples from 16 cancer types and identified six altered genes (RPL5, RPL11, RPL23A, RPS5, RPS20 and RPSA)." (PMID 28147343, 2017). "The most enriched KEGG pathways were related to the ribosome (RPS5, RPS9), focal adhesion signaling pathways (FGL, SPP1), synaptic vesicle cycle (CLTC), and ether lipid metabolism (ENPP2), which were related to the invasion and metastasis of cancer." (PMID 36276156, 2022).
tumor (10 papers, 2011 to 2024). "Through comprehensive analyses, we established a robust association between elevated RPS5 expression and advanced clinicopathological features, including tumor stage, histological grade, and prognosis, indicative of its potential as a prognostic biomarker." (PMID 38255847, 2024). "Correspondingly, Western blot experiments and IHC staining corroborated these results, confirmed elevated protein levels of RPS5 in HCC tissues compared to para-tumor tissues." (PMID 38255847, 2024). "RPS5 in combination with RPS19 (for tumor tissues) or HNRNPH (for cell lines) showed the highest expression stability compared to other genes such as B2M and GAPDH, which are the most commonly used reference genes in many human and canine OS studies to date." (PMID 29178874, 2017). "coli), RPLP0 (tumor progression, invasion, metastasis), RPS5, RPL9, RPS14, RPS2, RPL3, and RPL23." (PMID 34445327, 2021). "Initially, RPS5 mRNA levels were assessed using qRT-PCR in HCC and non-tumor tissues, revealing a significant up-regulation in 57.5% (23/40) of HCC samples." (PMID 38255847, 2024). "To further assess the impact of RPS5 on HCC tumorigenesis in vivo, we injected MHCC97H cells with stable RPS5 knockdown or control cells into the livers of nude mice, facilitating an examination of tumor growth in situ and lung metastasis." (PMID 38255847, 2024). "Therefore, our comprehensive analysis indicates that RPS5 displays abnormal overexpression across multiple HCC datasets, demonstrating a remarkably high correlation with factors such as tumor stage, histological grade, prognosis, and metastasis." (PMID 38255847, 2024). "Transcriptional profiles identified 39 genes that differentiated between 19 'metastatic' and 35 'non-metastatic' tumours, with molecular pathways involved in protein translation most strongly represented (MRPL33, RPL12, RPL27A, RPS5, RPS9)." (PMID 21385341, 2011).
RPS5 also shares sentences with these, for which no sentence is quoted: colon cancer (2 papers); Diamond-Blackfan anemia (2); abdominal aortic aneurysm (1); acute promyelocytic leukemia (1); B-cell lymphoma (1); cervical cancer (1); cystic fibrosis (1); diabetes (1); dwarfism (1); HCMV infection (1); injury (1); liver cancer (1); lupus nephritis (1); nerve sheath tumors (1); postmenopausal osteoporosis (1); prostate carcinoma (1); psoriasis (1); pulmonary fibrosis (1); renal clear cell carcinoma (1).